Y_RNA (Y RNA )
Gene: Miscellaneous RNA gene on chromosome 1 (89,020,246 to 89,020,365, reverse strand). Ensembl gene ENSG00000202385.
Homologues: Orthologues: chimpanzee Y_RNA (98% identical), macaque Y_RNA (95% identical). Paralogues in human: Y_RNA (79% identical), RNY1P2 (77% identical), Y_RNA (77% identical), Y_RNA (76% identical), Y_RNA (74% identical), Y_RNA (72% identical), RNY1 (72% identical), Y_RNA (71% identical), Y_RNA (70% identical), RNY1P5 (69% identical), Y_RNA (69% identical), Y_RNA (68% identical), and 86 more.